KEAP1 (kelch like ECH associated protein 1)
Diseases named in the same sentence as KEAP1 in open-access papers (continued):
Sharing a sentence is not in itself a finding about the gene and the disease.
cancer (continued). "KEAP1 (Kelch Like ECH Associated Protein 1, KLHL19) plays a major role in regulation of cellular oxidative stress in SkM and other tissues and contributes to cancer and other diseases." (PMID 33182325, 2020). "In addition, NFE2L2/KEAP1 mutations cause the constitutive activation of the NRF2 pathway and enhanced ARE activity, a feature suggested as being exploitable for a cancer suicide gene therapy." (PMID 33228209, 2020). "The glucose-induced glycation of NRF2 influences its protein-protein interaction properties and suppresses its oncogenic activity, while the MGO-induced glycation of the tumor suppressor KEAP1 causes the accumulation of NRF2 in cells and thus promotes cancer progression." (PMID 32356279, 2020). "However, inactivating mutations in KEAP1 that lead to constitutive NRF2 activation can provide a growth advantage in some cancer cells." (PMID 32938017, 2020). "Importantly, many diseases cause oxidative stress that can result in modification of KEAP1 cysteine residues and prompt NRF2 activation, including cancer, diabetes, neurogenerative disease, and inflammation-related diseases, among others." (PMID 33080927, 2020). "It is noteworthy that CB-839 dependent glutaminase inhibition, in the genetic context of KEAP1 mutation, suppressed tumor growth in a panel of human cancer cells with different origin, while NRF2 activation by KI696 treatment sensitized KEAP1-WT cells previously refractory to CB-839." (PMID 32443774, 2020). "The reduction of Keap1 protein levels in cancer cells is mostly due to the epigenetic alteration of Keap1 through the hypermethylation of the CpG islands in the Keap1 promoter region, which thereby releases Nrf2 from the inhibitory regulation of Keap1." (PMID 33050575, 2020). "Moreover the timing of NRF2 activation is crucial to understand its role: in cancers, it is chronically hyperactivated, whereas in normal tissue it is constantly repressed by KEAP1-dependent degradation and activated only in response to stress stimuli." (PMID 33233657, 2020). "Hence, MINERVA was suggested to act as an upstream regulator of Nrf2-mediated response to oxidative stress in cancer by hindering interaction of Keap1 and Nrf2 by competing for the Kelch domain through the “DLGXnETGE” motif." (PMID 33142954, 2020). "The Keap1-Nrf2 pathway is a regulator of cytoprotective responses to endogenous and exogenous stresses induced by ROS, which are an unenviable part of aerobic life, and its dysregulation is observed in cancer cells." (PMID 33197892, 2020). "For instance, KEAP1 encodes the adapter protein of an E3 ligase complex which can ubiquitinate NRF2, and previous studies have proven that mutations in KEAP1 and NFE2L2 may lead to NRF2 activation which may further contribute to spontaneous cancer development." (PMID 32434476, 2020). "Therefore, the decreased availability of Keap1 in the presence of increased levels of p62 can modify the balance of expression of several interactors, contributing to cancer progression." (PMID 32824383, 2020). "In cancer, imbalanced glycation could promote cancer by several mechniasms; the two recent transcription factor studies uncovered completely distinct biological implications of the NRF2/KEAP1 glycation pathway in cancer development." (PMID 32356279, 2020). "Interestingly, a significant translational impact in terms of increased risk of cancer progression and shorter overall survival was documented for alterations in the Kelch-like ECH-associated protein 1 (KEAP1) gene." (PMID 32971994, 2020). "In some cancer types, one or both Keap1 and Nrf2 are mutated, which does not allow a proper chemical interaction between the two." (PMID 31717324, 2019). "However, wild type and Keap1 null cancer cells have significant changes in metabolism, yet tumors derived from cells of these genotypes do not show significant alterations in levels of nutrients whose metabolism is known to be altered by Keap1 loss." (PMID 30990168, 2019).
cancer (continued). "Our study combines miRNA regulation of KEAP1 with cancer resistance." (PMID 31659154, 2019). "By summarizing the results from past and recent studies, in this review, we provide an overview concerning the NRF2/KEAP1 pathway, its biological impact in solid and hematologic malignancies, and the molecular mechanisms causing NRF2 hyperactivation in cancer cells." (PMID 31097977, 2019). "These previous findings suggested that inhibition of Keap1/Nrf2 pathway could be a target for anti‐cancer therapies." (PMID 30735010, 2019). "In cancer cells, because of chemical modifications of KEAP1 cysteine residues, the inhibition of ubiquitin conjugation to NRF2 by the KEAP1-CUL3 complex leads to NRF2-KEAP1 impairment and results in the nuclear accumulation of the de novo synthesized NRF2 protein." (PMID 31159323, 2019). "The close similarity among these compounds suggests that 1100‐50 and EM2487 may also exert anti‐cancer effects through Keap1/Nrf2 pathway inhibition." (PMID 30735010, 2019). "K‐563, a novel Keap1/Nrf2 pathway inhibitor, may be a lead compound for development as an anti‐cancer agent." (PMID 30735010, 2019). "Mutations in KEAP1 and/or NRF2 genes have been identified across many cancers and the dysregulation of the NRF2 pathway due to these mutations leads to drug and radioresistance in several cancers." (PMID 31839815, 2019). "Notably, KEAP1 is a well-known antioxidant gene that plays an important regulatory role in cancer survival or response to drug resistance." (PMID 31659154, 2019). "Silencing of KEAP1 gene by hypermethylation has been described in several cancers." (PMID 31428048, 2019). "While in normal cells the NRF2/Keap1 antioxidant pathway plays a crucial role in maintaining cellular homeostasis and preventing tumorigenesis, in cancer cells high expression of NRF2-regulated genes provides them with cytoprotection, contributing to their oncogenic capabilities." (PMID 29755668, 2018). "Moreover, nuclear EGFR phosphorylates Keap1 and reduces its nuclear protein level, stabilizing nuclear Nrf2 and increasing its transcriptional activity in cancer cells." (PMID 30595797, 2018). "In human cancers, similar to NFE2L2, KEAP1 mutations would disrupt the normal combination of NFE2L2 and KEAP1 in tumors, resulting in accumulation of excessive intracellular NFE2L2 and activation of its downstream genes and the eventual promotion of tumor growth." (PMID 29484121, 2018). "Importantly, co-treatment with KI696 was able to sensitize KEAP1 wild type cancer cells that were relatively insensitive to CB-839." (PMID 28967864, 2017). "Notably, mutations in KEAP1, NRF2, and PTEN are mutually exclusive and are seldom found in the same cancer cell." (PMID 28523248, 2017). "Importantly, increased expression of WDR23 in KEAP1(-/-) cancer cells restores aberrant NRF2 regulation." (PMID 28453520, 2017). "Our data, when combined with the information archived at the COSMIC from human somatic tumors, strongly supports the prediction that enhancing the WDR23 pathway could reestablish regulation of activated NRF2 in KEAP1(-/-) cancer cells." (PMID 28453520, 2017). "Activating mutations in Nrf2, inactivating mutations in KEAP1, and epigenetic dysregulation of KEAP1 and NFE2L2 have been observed in various types of cancers, and these changes are more common in cells and tissues that demonstrate de novo or acquired resistance to various types of chemotherapy." (PMID 28383481, 2017). "Since UHRF1 over‐expression occurs in other cancers, its ability to regulate the Keap1–Nrf2 pathway may be critically important to the malignant behaviour of these cancers." (PMID 26497117, 2016).
cancer (continued). "So, if the activity of Keap1 is impaired, which can lead to full Nrf2 activation, cancer cells may acquire a protective mechanism against the surrounding microenvironment." (PMID 27029077, 2016). "Compounds such as oltipraz and sulforaphane which interfere with the Keap1-Nrf2 interaction to activate target genes without causing cell stress, are effective as cancer chemo-preventive agents in animal experiments." (PMID 27233051, 2016). "Since UHRF1 is over‐expressed in several other cancers, its ability to regulate Keap1–Nrf2 may be important in their pathogenesis." (PMID 26497117, 2016). "Besides DNA methylation, miRNA-induced silencing is another mechanism for modulating Keap1–Nrf2 pathway in cancer." (PMID 27200299, 2016). "As to Keap1, its role in cancer varies with the stages in the multistep carcinogenesis process." (PMID 27200299, 2016). "Together, the involvement of p21 and p62 in the regulation of KEAP1/NRF2 lends a good support for the assumption that modulating the NRF2/ARE signaling pathway is critical in executing the cell-cycle arrest or autophagy in cancer." (PMID 27340506, 2016). "Concomitant abnormalities of oncogenes and KEAP1 gene may affect tumorigenesis and accelerate the growth of cancer cells." (PMID 27703446, 2016). "Dysregulation of Keap1–Nrf2 pathway in cancer can also be mediated by metabolites." (PMID 27200299, 2016). "Consequently, the Keap1–Nrf2 system has emerged as an important therapeutic target in cancer and neurodegenerative conditions, as well as many autoimmune and inflammatory diseases." (PMID 26057936, 2015). "The reasons behind the overactivation of Nrf2 in cancer cells are not well clear, although several potential mechanisms have been proposed such as Keap1 mutation that will accumulate Nrf2 in the nucleus and preventing also its re-uptake." (PMID 25699252, 2015). "The results from this study demonstrate that treatment with an AIM does not have the same effect as KEAP1 loss or mutation on cancer cell growth and survival." (PMID 26301506, 2015). "It should be noted that Keap 1 is an important target for the bioactivity of XN, such as cancer chemo-prevention, hepatic protection, anti-inflammation, because alkylation on Keap1 activates antioxidant enzymes, such as quinine reductase, NQO1, HO-1, via the regulations of Nrf2." (PMID 25574819, 2015). "There are no recognized germ-line mutations of Keap1, but somatic mutations have been reported in various carcinomas." (PMID 25879528, 2015). "Although the cytoprotective system is designed to prevent normal cells from becoming cancerous, in a cisplatin-induced ROS-rich environment, cancer cells may hijack the Keap1/Nrf2 system and induce AKR1C2 protein expression as an antioxidant substance." (PMID 24527071, 2014). "Thus, discovery and development of Nrf2 inhibitors based on the molecular mechanisms of the Keap1-Nrf2 system is one of the most critical and challenging assignments for conquering cancers." (PMID 24386210, 2013). "In this context, NRF2 may be a potential molecular target for the treatment of radio-resistance cancers, especially those that have “loss of function” mutations in EGFR, KRAS, or KEAP1 as well as “gain of function” mutations in NRF2." (PMID 23936606, 2013). "Mutations activating Nrf2 or inactivating the inhibitor of Nrf2, Keap1, are found in human cancers." (PMID 22848625, 2012). "The Keap1-Nrf2 pathway has been reported to be impaired in several cancers." (PMID 22325485, 2012). "Hayes and coworkers previously suggested that Keap1 knockdown with RNAi might be a potentially useful strategy for cancer chemoprevention." (PMID 22558124, 2012). "Recent research suggests that pharmacological intervention using dietary factors that activate the redox sensitive Nrf2/Keap1-ARE signaling pathway may represent a promising strategy for chemoprevention of human cancer including CRC." (PMID 20657484, 2010).
cancer (continued). "However, KEAP1 LOF mutations or inactivation may disrupt this regulation, leading to NRF2 accumulation and sustained activation of pathways supporting cancer cell survival, including antioxidant synthesis, xenobiotic metabolism, and drug efflux." (PMID 41541668, 2026). "This study provides new insights that CAP is a safe and novel NRF2 agonist by allosterically regulating KEAP1, which may contribute to the development of lead drugs for oxidative stress-related illness, e.g., aging, cancer, neurodegenerative, and cardiovascular diseases." (PMID 42262974, 2026). "Conversely, persistent or constitutive activation—often due to mutations in KEAP1 or Nuclear factor erythroid 2-like 2 (NFE2L2) which encodes NRF2, or metabolic rewiring—confers a tumor-promoting phenotype, enhancing survival, proliferation, and treatment resistance in established cancers." (PMID 41470226, 2025). "However, the underlying mechanisms regarding the regulation of Keap1/Nrf2/ARE pathways during ER stress as well as cancer chemoresistance have not been fully elucidated." (PMID 40735463, 2025). "Genetic inactivation of KEAP1, or gain-of-function mutations in the NFE2L2 gene which encodes NRF2, produce highly malignant tumours which can evade the anti-cancer immune response, and are resistant to all existing anti-cancer therapies, including immune checkpoint inhibitors." (PMID 40890297, 2025). "Currently, most studies on ferroptosis focus on malignant tumors and degenerative diseases, with mechanistic studies primarily focusing on abnormalities in iron metabolism, lipid peroxidation, and the Kelch-like ECH-associated protein 1(Keap1)-Nuclear factor E2-related factor 2 (Nrf2) pathway." (PMID 39754066, 2025). "However, hyperactivation of NRF2, due to mechanisms such as KEAP1 mutations or elevated NRF2 expression, can benefit cancer cells by protecting them from excessive oxidative stress and therapeutic agents, thereby promoting cancer cell survival." (PMID 40802750, 2025). "Thus, understanding the impact of KEAP1 modulation on PD-L1 expression is significant for the development and efficacy of therapeutic approaches targeting both oxidative stress and immune checkpoints in cancer treatment." (PMID 38413563, 2024). "In lung tumors, the growth and the progression of cancer cells may also involve the intersection between the molecular NRF2/KEAP1 axis and other pathways, including NOTCH, with implications for antioxidant protection, survival of cancer cells, and drug resistance to therapies." (PMID 38791966, 2024). "In addition, KEAP1 (Kelch-like ECH-associated protein 1)/NRF2 (nuclear factor erythroid 2-related factor 2) signaling, recognized as one of the most important antioxidant regulators, plays a multifaceted role in the initiation and progression of some cancers." (PMID 39061847, 2024). "Thus, SLC7A11 and GCLC expression could be defined as a cancer signature of GAS41 amplification in NSCLC (KEAP1 and NFE2L2 WT)." (PMID 38514704, 2024). "Therefore, KEAP1 is a crucial regulator in cell response to cancer therapy." (PMID 37251921, 2023). "Furthermore, NRF2 plays an important role in cancer prevention and progression; activation of NRF2/KEAP1 signaling in cancer cells results in chemoresistance, inactivating drug-mediated oxidative stress, and protecting cancer cells from drug-induced cell death." (PMID 37298147, 2023). "Therefore, BT may be indicated as a cancer-specific multi-modal small molecule for increasing drug responsiveness in LUAD cells by maintaining NRF2/KEAP1 signaling at an optimum threshold level." (PMID 37305533, 2023). "Using real-world data, we assessed the effect of KRAS G12C mutation with or without STK11 and/or KEAP1 mutations on overall survival (OS) in patients with aNSCLC receiving cancer immunotherapy (CIT), chemotherapy, or both in first line (1L) and second line (2L)." (PMID 37069542, 2023).
cancer (continued). "The Nrf2/KEAP1 pathway has also been described as one of the crucial regulators of cancer cell metabolism leading to the production of metabolites which may improve the proliferation and survival of cancer cells, leading to the reprogramming of intracellular anabolic and catabolic metabolism." (PMID 36771023, 2023). "This indicates that there is an opportunity for therapeutic intervention by targeting CDO1 in particular cancer contexts in which CDO1 silencing is not occurring as it was described that CDO1 silencing by methylation was occurring preferentially in KEAP1-mutated cases in NSCLC." (PMID 38247476, 2023). "Therefore, activation of NRF2/KEAP1 signaling may lead to distinct even opposite outcomes in cancer and therapeutic strategies targeting this pathway must be cautiously assessed according to the context." (PMID 35754474, 2022). "Consequently, inhibiting the Keap1/Nrf2/HO-1 antioxidant pathway may be a suitable strategy to promote ferroptosis in cancer cells." (PMID 35350242, 2022). "However, the dual roles of NRF2/KEAP1 signaling in cancer must be taken into consideration." (PMID 35754474, 2022). "Accordingly, in rapidly dividing cancer cells where ROS production is high, or in the process of ageing where there are marked decreases in antioxidant capacity, Nrf2, Keap1, and other proteins may be over-oxidized, resulting in dysregulated, and possibly enhanced, antioxidant activity." (PMID 35204126, 2022). "Thus, activating NRF2/KEAP1 signaling to protect cells from ROS has been widely acknowledged as a promising therapeutic strategy to alter redox equilibration of ROS-related chronic diseases, including cancer." (PMID 35754474, 2022). "Our hypothesis was that, in addition to DPP III overexpression, some DPP III mutations found in the human tumor genomes might be involved in the progression of cancer by changing its affinity for KEAP1, and subsequently affecting the KEAP1-NRF2 signaling pathway." (PMID 35216111, 2022). "However, sustained Nrf2 activation by impairment in autophagy and increase in p62 phosphorylation promotes antineoplastic drug chemoresistance as well as cancer cell proliferation, whereas mutation in KIR domain in p62, which prevents Keap1-p62 interaction, is associated with an ROS increase." (PMID 35052602, 2021). "Besides somatic mutations, epigenetic changes at KEAP1 and NFE2L2 promoters may promote to the accumulation of NRF2 and depletion of KEAP1 in cancer cells." (PMID 33808001, 2021). "Somatic mutations of the KEAP1 gene, causing the constitutive activation of NRF2, were found among lung cancer patients and confer a robust growth advantage and tumor-initiating ability on cancers through the promotion of metabolic reprogramming and enhancement of cancer stemness." (PMID 33535386, 2021). "While the KEAP1-Nrf2 pathway might appear as an independent pathway, the mTORC1-cMYC and the KEAP1-Nrf2 pathway are tightly interconnected and act synergistically in cancer initiation driven by ROS accumulation." (PMID 33754045, 2021). "Thus, the role of Nrf2 and its negative regulator, Keap1, has stimulated many studies in the field of cancer to find out whether the activation of this pathway could be a good strategy for cancer treatment." (PMID 33053665, 2020). "Therefore, it is pointed out that the modulation of the KEAP1/NRF2/ARE pathway may modulate the risk of lifestyle diseases, such as cancer." (PMID 32455559, 2020). "The latest emerging roles of non-promoter CpG islands of cancer-related genes and the translational impact of KEAP1/NRF2 point mutations in predicting resistance to treatment further beg the question of the translational utility of KEAP1 methylation in the clinical context." (PMID 32971994, 2020). "The stage of cancer at which mutations in NFE2L2 and KEAP1 arise is currently unknown." (PMID 33276631, 2020).